MT-TQ (mitochondrially encoded tRNA-Gln (CAA/G))
Synonyms: trnQ; formerly MTTQ
Gene: Mitochondrial transfer RNA gene on chromosome MT (4,329 to 4,400, reverse strand). Ensembl gene ENSG00000210107.
Gene Ontology:
Molecular function: triplet codon-amino acid adaptor activity
Biological process: translation
Gene-disease validity (ClinGen):
ClinGen rates the evidence that MT-TQ causes each of these diseases.
mitochondrial disease (mitochondrial): Limited.